ANXA6 (annexin A6)
Diseases named in the same sentence as ANXA6 in open-access papers (continued):
Sharing a sentence is not in itself a finding about the gene and the disease.
limb-girdle muscular dystrophy (1 paper, 2015). Limb-girdle muscular dystrophy (LGMD) is a heterogeneous group of muscular dystrophies characterized by proximal weakness affecting the pelvic and shoulder girdles. "However, annexin A6, an annexin A1-related gene, has been recently identified as a modifier and a membrane repair factor of Limb-Girdle muscular dystrophy." (PMID 25775477, 2015).
liver cirrhosis (1 paper, 2012). "We have specifically identified annexin A3 and annexin A6 as a potential biomarker for predicting alcohol-induced liver cirrhosis." (PMID 22682408, 2012). "Further investigation of the function mechanism of ANXA3 and ANXA6 in liver cirrhosis may yield new clues to the molecular mechanism of alcohol-induced liver disease." (PMID 22682408, 2012).
liver dysfunction (1 paper, 2021). "In addition, drug-induced AnxA6 upregulation, delivery of recombinant AnxA6 or AnxA6-targeting antibodies might lead to the development of novel treatment options in lipid disorders, liver dysfunction, several cancers and muscular damage (Section 7.4, Section 7.5 and Section 7.6)." (PMID 33810523, 2021).
myocardial diseases (1 paper, 2025). "We also found potentially pathologic mutations in genes ANXA6 and FEM1 A and obtained data supporting the role of NEBL in myocardial diseases." (PMID 40442228, 2025).
myocarditis (1 paper, 2022). Myocarditis is a condition that is characterized by inflammation of the heart muscle (myocardium). "AnxA6 is strongly expressed in the heart and mice overexpressing AnxA6 have enlarged dilated hearts with lymphocytic infiltration and severe fibrosis, acute diffuse myocarditis, and mild fibrosis in pulmonary veins." (PMID 36313572, 2022).
nonalcoholic fatty liver disease (1 paper, 2025). "In a data set related to nonalcoholic fatty liver disease (GSE135251), Anxa6 mRNA levels were significantly elevated in both nonalcoholic fatty liver (NAFL) and nonalcoholic steatohepatitis (NASH) liver of patients across different disease stages." (PMID 40802799, 2025).
respiratory failure (1 paper, 2017). The significant impairment of gas exchange within the lungs resulting in hypoxia, hypercarbia, or both, to the extent that organ tissue perfusion is severely compromised. "Right ventricular hypertrophy, a frequent association with respiratory failure in DMD patients, may be, in part, a direct effect of altered annexin A6 expression, as annexin A6 is highly expressed in both skeletal muscle and myocardium." (PMID 29367543, 2017).
spontaneous abortion (1 paper, 2025). Expulsion of the product of FERTILIZATION before completing the term of GESTATION and without deliberate interference. "ANXA6 is involved in numerous biological processes; however, its association with recurrent spontaneous abortion (RSA) remains poorly understood." (PMID 40959268, 2025).
transient cerebral ischemia (1 paper, 2024). "This study is the first to suggest that ANXA6 enhances synaptic plasticity and protects against transient cerebral ischemia." (PMID 38380783, 2024).
tumor (72 papers, 1995 to 2026). "Together, there data indicated SUMOylation-deficient AnxA6 had lost tumor-suppressor activity in vivo." (PMID 37528485, 2023). "The protein ANXA6 has been implicated in various cellular functions including cell growth, differentiation and motility, which underlie tumor progression." (PMID 37189694, 2023). "This is consistent with the association of AnxA6 expression in tumor cells with relatively slower growth and resistance to chemotherapy." (PMID 36230969, 2022). "In a TNBC model using BT-549 xenografts, AnxA6 depletion was associated with early onset and rapid growth of tumours, which correlated with poor overall survival of basal-like TNBC patients." (PMID 33810523, 2021). "While these studies suggest a potential role of AnxA6 in energy metabolism especially in rapidly growing tumor cells, the molecular details and underlying mechanism(s) remain to be fully elucidated." (PMID 32784650, 2020). "As a Ca2+ and membrane binding protein, AnxA6 is implicated in a wide range of cellular functions including cell growth, differentiation and motility which underlie tumor progression." (PMID 32298357, 2020). "To validate the early xenograft tumor onset of AnxA6 deficient BT-A6A cells, we demonstrate that injection of fewer cells delayed tumor onset in a dose dependent manner followed by rapid growth of the ensuing xenograft tumors." (PMID 30719209, 2019). "The further decrease in the expression of CD24 and up-regulation of JAG1 following AnxA6 down-regulation suggest that reduced expression or loss of AnxA6 is associated with poorly differentiated, highly proliferative tumor cells." (PMID 30719209, 2019). "To test this, we stained the tumor tissues derived from the BT-A6sh5 cells and AnxA6-deficient BT-A6A cells by immunohistochemistry." (PMID 30719209, 2019). "In summary, reduced expression of AnxA6 appears to be a critical event in breast carcinogenesis, as loss of AnxA6 is associated with early onset and rapid tumor growth." (PMID 30719209, 2019). "The enhanced growth of AnxA6-deficient tumor cells on the other hand is currently believed to be driven by the high cytosolic Ca2+-induced activation of PKC isoforms that in turn activate the Ras pathway independently of EGFR activity." (PMID 24354805, 2013). "Together this demonstrates that the rapid degradation of activated EGFR in AnxA6-depleted invasive tumor cells underlies their sensitivity to EGFR-targeted TKIs and reduced motility." (PMID 24354805, 2013). "This also suggests that AnxA6 expression is associated with cell motility while reduced AnxA6 expression is associated with enhanced tumor cell growth." (PMID 24354805, 2013). "Together, this demonstrates that the rapid degradation of activated EGFR in AnxA6-depleted invasive tumor cells underlies their sensitivity to EGFR-targeted TKIs and attenuated motility." (PMID 24354805, 2013). "The expression of annexin A6 (AnxA6) in AnxA6-deficient non-invasive tumor cells has been shown to terminate epidermal growth factor receptor (EGFR) activation and downstream signaling." (PMID 24354805, 2013). "As previously reported in other AnxA6-deficient tumor cells, over expression of AnxA6 in HCC1806 cells on the other hand was associated with reduced activation of the receptor and ERK1/2." (PMID 24354805, 2013). "Also, tumor-supporting cells, like cancer-associated fibroblasts, release EVs containing Annexin A6, miR-21, or lncRNA H19, which contributes to the development of stem-like properties and resistance to chemotherapy in tumor cells." (PMID 38796692, 2024). "Increasingly studies have shown that ANXA6 plays an essential role in the formation and development of various cancers and has a specific impact on various tumor-associated phenotypes, such as proliferation, migration, invasion, drug resistance, and metabolic reprogramming." (PMID 37129645, 2023). "Many studies have indicated that ANXA6 is associated with tumor drug resistance." (PMID 37129645, 2023).
tumor (continued). "In mouse TNBC xenografted models, the loss of ANXA6 is associated with tumorigenesis and development, and ANXA6 may inhibit tumor proliferation in TNBC cells." (PMID 37129645, 2023). "This and additional scaffolding functions that inhibit oncogenic signalling cascades could also contribute to AnxA6 tumor suppressor functions in other cancers with diagnostic value for tumor malignancy and progression." (PMID 35806209, 2022). "These included cancer epigenetic targets previously implicated in tumor suppressive activity such as ANXA6 [annexin A6], VANGL2 [VANGL planar cell polarity protein 2], BIN1 [bridging integrator 1], and CREB3L1 [cAMP responsive element binding protein 3 like 1]." (PMID 34074348, 2021). "Here, we selected the poorly tumorigenic BT-549 TNBC cells (tumor latency 2–3 months) to test the hypothesis that reduced expression of AnxA6 is associated with tumor growth." (PMID 30719209, 2019). "Although these studies emphasize the notion that detection of AnxA6 in several cancers might have diagnostic value, the effects of AxA6 suggest that it may act as either a tumor suppressor or a tumor promoter, depending on the type of cancer and stage of the disease." (PMID 32784650, 2020). "Although other mechanisms may be involved, our study supports the notion that the tumor associated functions of AnxA6 hinge on its ability to modulate the activity of Ca2+ influx channels and to aggregate factors that mediate the activation of small GTPases including Ras, Cdc42 and Rac." (PMID 30719209, 2019). "Mechanistically, tumor-derived CypA specifically from PCa cells bound to ANXA6 and activated the downstream FPR1 signaling pathway, leading to increased mitochondrial oxidative phosphorylation and NK cell activation." (PMID 41591831, 2026). "ANXA6 mediates cholesterol transport and participates in endocytosis and exocytosis and can serve as a tumor suppressor due to its ability to negatively regulate EGFR phosphorylation." (PMID 40188944, 2025). "Then we detected the background expression of ANXA6 in Caco-2 tumor cells and observed significantly higher ANXA6 expression compared to human intestinal epithelial cells (HIEC) (data not shown)." (PMID 41522448, 2025). "In a typical TNBC tumor, the probability for co-expression of AnxA6 and vimentin is higher than with Ki67 or between AnxA6 and Ki67 and supports the use of vimentin and AnxA6 as bona fide markers of invasiveness." (PMID 41279138, 2025). "There were discrete tumor patches e.g. tumor area A with high expression of AnxA6 and low expression of Ki67 (AnxA6hi/Ki67lo) with ~14% Ki67 positivity, while the bulk of the tumor represented by tumor area B showed AnxA6lo/Ki67hi with >36%Ki67 positivity." (PMID 41279138, 2025). "This process was mediated, at least in part, by tumour-derived extracellular vesicles enriched in annexin-A6 (ANXA6)." (PMID 38674115, 2024). "As a member of the annexin family, AnxA6 role in cancer development is rather complicated, it acts as a promoting factor in some cancers and is also considered to exert tumor-suppressing activities." (PMID 38566133, 2024). "Increased PDAC aggressiveness was dependent on the tumor cell-mediated uptake of CAF-derived ANXA6-positive EVs carrying the ANXA6/LRP1/THBS1 complex." (PMID 38892190, 2024). "Other molecules involved in tumor cell aggressiveness and proliferation are annexin A6 (ANXA6) and adrenomedullin, which increase proliferation and invasion, both released by pancreatic stellate cells via EVs." (PMID 38790954, 2024). "To further validate the correlation between AnxA6 expression profiling and tumor grade, we performed IHC analysis in 15 HCC tissues with different tumor stages and patients’ autologous adjacent tissues." (PMID 38566133, 2024). "ANXA6 is currently known to mediate different patterns of tumor progression in different cancer types through multiple cancer-type specific mechanisms." (PMID 37129645, 2023).
tumor (continued). "More interestingly, AnxA6 exhibits dual functions either as a tumor suppressor or oncogene in carcinogenesis, which is dependent on its recruitment of different target proteins to involve in cancer cell activities." (PMID 37528485, 2023). "ANXA6-EVs up-regulate yes-associated protein (YAP) to promote dysregulation of the Hippo pathway, contributing to the development of tumor resistance to some extent." (PMID 37129645, 2023). "At 21 days of inoculation, AnxA6 knockdown in HeLa cells significantly promoted tumorigenesis and tumor growth." (PMID 37528485, 2023). "This review mainly summarizes recent findings on the mechanism of tumor formation, development, and drug resistance of ANXA6." (PMID 37129645, 2023). "ANXA6 is differentially expressed in various tumors and is widely involved in multiple phenotypes, including tumor formation, progression, drug resistance, metabolic reprogramming, and other related phenotypes." (PMID 37129645, 2023). "Annexin A6 has dual functions, acting either as a tumour promoter or tumour suppressor depending on the type of cancer or malignancy." (PMID 37833989, 2023). "Many studies have shown that annexins, especially ANXA6, play an important role in tumor formation, development, and drug resistance." (PMID 37129645, 2023). "When TNBC cells are chronically exposed to Lapatinib or other TKIs targeting EGFR, this is accompanied by ANXA6 upregulation and LE/Lys-Chol accumulation, ultimately leading to tumor resistance." (PMID 37129645, 2023). "In pheochromocytoma cell line P12, ANXA6 overexpression can increase intracellular Ca2+ levels, decrease catecholamine secretion and promote tumor migration." (PMID 37129645, 2023). "ANXA6 exhibits a dual role in different tumors, acting as a tumor suppressor or promoter depending on the cancer type and malignancy." (PMID 37129645, 2023). "A larger tumor volume with 435.1 ± 185.6mm3 and tumor weight with 0.22 ± 0.08 g was respectively observed in HeLa-AnxA6(KD)-injected mouse than HeLa-xenografted tumor with 204.0 ± 63.9mm3 volume and 0.09 ± 0.03 g weight." (PMID 37528485, 2023). "While this partially explains the poor efficacy of this class of drugs especially in AnxA6-low basal-like TNBCs, the role of other confounding factors including hypoxia in rapidly growing tumor cells remained unclear." (PMID 36230969, 2022). "In most cases, ANXA6 acts as a tumor suppressor, but some oncogenic roles have also been described depending on the cancer type and disease stage." (PMID 36247003, 2022). "Although the expression status of AnxA6 has been shown to influence tumor growth, metastasis and resistance to therapeutic intervention, the contribution of this tumor suppressor in the metabolic adaptation of TNBC cells remains poorly understood." (PMID 35267416, 2022). "Recent studies on AnxA6 have shown that reduced expression promotes rapid tumor growth, affecting several aspects of energy metabolism." (PMID 36230969, 2022). "Ectopic expression of ANXA6 in the human A431 squamous epithelial carcinoma cells reduced tumor growth suggesting an antitumor role for ANXA6 in A431 cells." (PMID 36247003, 2022). "ANXA6 is required for the cell-cell and cell-ECM contacts, and its loss contributes to tumor progression by promoting loss of cell contacts and anchorage-independent growth." (PMID 36247003, 2022). "Numerous studies identified AnxA6 to exhibit tumour suppressing as well as tumour promoting activities, depending on the cancer cell type and degree of malignancy." (PMID 33810523, 2021). "These interactions suggest the involvement of AnxA6 in cellular signaling mechanisms that ultimately lead to tumor cell growth, motility and differentiation." (PMID 32784650, 2020). "Contrary to its role in the proliferation of tumor cells, the expression status of AnxA6 appears to differentially influence the motility of tumor cells in a cell-type- or cancer-type-dependent manner." (PMID 32784650, 2020).
tumor (continued). "Together with the secretion of AnxA6 as a component of extracellular vesicles, this suggests that AnxA6 mediates distinct tumor progression patterns via extracellular and/or intracellular activities." (PMID 32784650, 2020). "Remarkably, several other cell-based studies have suggested a critical role of extracellular AnxA6 in tumor cell motility and invasiveness, as well as cancer metastasis in vivo." (PMID 32784650, 2020). "We also observed that these GEVs downregulated annexin A6 (p=0.024), which has been shown to support tumor invasiveness and aggressiveness across multiple cancers 32,33." (PMID 32642004, 2020). "As a Ca2+-dependent membrane-binding protein, AnxA6 has been shown to be involved in several cellular functions that define tumor cell growth." (PMID 32784650, 2020). "Over the years, several studies have examined the effects of AnxA6 on hallmarks of cancer such as growth, motility and differentiation in several tumor cell models." (PMID 32784650, 2020). "AnxA6 is differentially expressed in various stages/subtypes of several cancers, and its expression in certain tumor cells is also induced by a variety of pharmacological drugs." (PMID 32784650, 2020). "In these tumors and in basal-like TNBCs in particular, AnxA6 appears to act as a tumor suppressor, as reduced expression of AnxA6 led to the rapid growth of xenograft tumors and was associated with poor overall survival of basal-like TNBC patients." (PMID 32784650, 2020). "Several lines of evidence from our studies and other reports suggest that AnxA6 expression levels are also regulated following the treatment of tumor cells with a variety of pharmacological drugs." (PMID 32784650, 2020). "Two broadly used cytotoxic drugs, taxanes and anthracyclines, were found to enhance the pro-metastatic ability of tumor-derived EVs, which were enriched with annexin A6 (ANXA6), a protein that promotes the activation of NF-κB-dependent endothelial cells." (PMID 33628730, 2020). "The proteomic signature of the stromal components of PDA identified the annexin A6/LDL receptor-related protein 1/thrombospondin 1 (ANXA6/LRP1/TSP1) as crucial for tumour cell crosstalk within the TME." (PMID 32942702, 2020). "Analysis of tumor growth revealed that up-regulation of AnxA6 inhibited the growth of xenograft tumors, consistent with its tumor suppressor function." (PMID 30719209, 2019). "As a member of the annexin family of Ca2+ dependent membrane binding proteins, AnxA6 is believed to be a tumor suppressor in many solid tumors." (PMID 30719209, 2019). "There is substantial evidence that AnxA6 is a tumor suppressor in many tumor types and that it promotes cell adhesion and motility, however the underlying mechanisms remain poorly understood." (PMID 30719209, 2019). "For example, MES GBMs (red arrows) were enriched for CAV1, CD44, CD63, RAB27A, SDCBP and SMPDL3A, while PN (blue arrows) tumours contained higher levels of transcripts for ANXA6, CD81, hnRNPA2B1, YBX1 (RNA binding proteins) and RAB35." (PMID 30034643, 2018). "Annexin A6 acts either as a tumour suppressor or promoter, depending on the type of cancer and the degree of malignancy." (PMID 29462943, 2018). "The inhibition of tumor cell proliferation following the expression of AnxA6 in AnxA6-low cells has been shown to be partly due to the inactivation of activated EGFR and the termination of EGFR-mediated activation of the Ras pathway." (PMID 24354805, 2013). "The resulting increase in cytosolic Ca2+ in these cells underlies at least in part, the increased contractility of cardiomyocytes and enhanced proliferation of tumor cells as well as AnxA6-modulation of tumor cell proliferation, differentiation and motility." (PMID 24354805, 2013). "Moreover, the deSUMOylated AnxA6 enhances cell migration and tumor development of HCC in vitro and in vivo." (PMID 38566133, 2024). "Inhibiting these CD9-positive ANXA6-EVs could potentially reduce stromal modification and tumor progression." (PMID 38542378, 2024).